MUC4 (mucin 4, cell surface associated)
Diseases named in the same sentence as MUC4 in open-access papers (continued):
Sharing a sentence is not in itself a finding about the gene and the disease.
pancreatic cancer (continued). "To examine the roles of MUC1 and MUC4 in IL-17RB-mediated stemness in the pancreatic cancer cells, we overexpressed FLAG-tagged IL-17RB, followed by knockdown of MUC1 and MUC4 by lentivirus-based shRNA in SU.86.86 cells." (PMID 33082357, 2020). "The present work demonstrates that activation of IL-17RB signaling confers pancreatic cancer cells with enhanced cancer stem-like property and resistance to gemcitabine treatment via enhanced MUC1 and MUC4 expression." (PMID 33082357, 2020). "Mucins, especially the highly-glycosylated MUC1, MUC4, MUC5AC, and MUC16, are prominently observed in pancreatic cancer and major carriers of glycans including the CA 19-9 antigen." (PMID 32582529, 2020). "The results of this study confirmed findings from previous studies that showed MUC4 expression in intraductal papillary mucinous neoplasm (IPMN) of the pancreas and pancreatic cancer with increased MUC4 expression in advanced stage of the disease." (PMID 34164227, 2018). "We analyzed MUC4, MUC16 and MUC20 expression in pancreatic tumor (T) and paired adjacent non tumoral tissues (ANT) from GSE28735 and GSE16515 (not shown) datasets." (PMID 30236127, 2018). "MUC4 and HER2 interactions are of importance in the progression of a variety of epithelial tumors including breast cancer and pancreatic cancers, where eosinophils, in particular EPO are also a feature." (PMID 27519953, 2016). "In pancreatic cancer cells, miR-150 was shown to bind to the 3′-UTR of c-Myb and MUC4 to regulate cell proliferation, migration and invasion." (PMID 26871477, 2016). "To prove this we transiently inhibited endogenous EGFR using siRNA in pancreatic cancer cells and, as expected, transient knockdown of EGFR expression led to inhibition of phospho-STAT1 thereby down regulating MUC4 mucin protein expression." (PMID 25686822, 2015). "Reciprocal co-immunoprecipitation assay showed that HER3 interacts with MUC4 in sh-Control and HER2-knockdown pancreatic cancer cells." (PMID 26035354, 2015). "Transmembrane proteins MUC4, EGFR and HER2 are shown to be critical in invasion and metastasis of pancreatic cancer." (PMID 25686822, 2015). "We have previously reported that MUC4/HER2 interaction plays an important role for proliferation and metastasis of pancreatic cancer cells." (PMID 26035354, 2015). "Among the several members of the mucin family, expression of MUC1, MUC4, and MUC5AC were found to be significantly elevated in the malignant stage of pancreatic cancer." (PMID 26046375, 2015). "In order to find out the distribution of MUC4 and HER3 in pancreatic cancer cells, we performed confocal microscopy analysis." (PMID 26035354, 2015). "A member of the transmembrane mucin family, mucin 4 (MUC4) has been mapped to chromosome 3 in the q29 region, which was cloned from the human tracheobronchial chromosomal DNA library and a human pancreatic tumor cell line." (PMID 25367394, 2014). "As MUC4 is one of the most differentially expressed proteins in pancreatic cancer and has been associated with the Herceptin resistance in breast cancer; the failure of HER2 trial in pancreatic cancer could possibly be attributed to MUC4 aberrant overexpression, which requires further investigation." (PMID 25261375, 2014). "Several studies have shown that aberrant and increased expression of MUC4 and MUC16 occurs during pancreatic cancer progression to metastasis." (PMID 24204560, 2013). "The transmembrane mucins, MUC4 and MUC16, are aberrantly overexpressed in many adenocarcinomas, including human pancreatic cancer." (PMID 24204560, 2013). "Our results show that ErbB2 and MUC4, which interact physically, activate different intracellular signalling pathways to regulate biological properties of CAPAN-2 pancreatic cancer cells." (PMID 22393391, 2012). "Altogether, these results indicate that MUC4 and ErbB2 physically interact in CAPAN-2 pancreatic cancer cells via MUC4EGF3+1+2 region that contains the three EGF-like domains." (PMID 22393391, 2012).
pancreatic cancer (continued). "In our previous study, we showed that MUC4 interacts and stabilizes HER2 in both ovarian and pancreatic cancer cells." (PMID 21521521, 2011). "In our previous studies we have shown that MUC4 interacts with HER2 in ovarian cancer and pancreatic cancer cells." (PMID 21521521, 2011). "Our recent finding showed that an overexpression of MUC4 increases the expression of HER2 in ovarian cancer cells and stabilizes the HER2 oncoprotein in pancreatic cancer cells." (PMID 21521521, 2011). "Since TGF-β2 is markedly induced by retinoids in other cancers and mediates MUC4 expression in pancreatic cancer cells, we investigated the role of TGF-β in retinoic acid-mediated growth inhibition in pancreatic cancer cells." (PMID 18157915, 2007). "Herein, we discuss the factors that contribute to the lethality of pancreatic cancer as well as the key role played by mucins, particularly MUC1 and MUC4, in the development and progression of the disease." (PMID 15494719, 2004). "A now well-established target in PDACs is Mucin 4 (MUC4), a large cell surface mucin that is exclusively expressed in pancreatic neoplasms but not in normal pancreatic tissue (center)." (PMID 40649822, 2025). "The lack of MUC4 expression in the normal pancreas and its expression in early stages of pancreatic cancer make it an excellent tumor-specific target for use in FGS as well as a potential tumor biomarker." (PMID 39458160, 2024). "MUC4 is generally not detectablein normal pancreas, but is highly expressed in the vast majority of pancreatic neoplasms, such as pancreatic ductal adenocarcinoma." (PMID 37771441, 2023). "In pancreatic cancer, MUC1, MUC4, and MUC 5AC mediate GEM sensitivity 29-31." (PMID 37324940, 2023). "MUC4: MUC4 is a high molecular weight glycoprotein that is over-expressed in pancreatic cancer tissues but not in pancreatic inflammatory diseases." (PMID 37760400, 2023). "The results showed that the overall expression level of mucin family and the patients with positive or high expression of MUC4 and MUC16 had a poor prognosis, indicating that mucin family can be used as a potential biomolecule to predict the prognosis of patients with pancreatic cancer." (PMID 35709153, 2022). "Graviola suppressed mucin 4 (MUC4) and HIF-1α-mediated expression of glycolytic genes and VEGF to promote tumor cell necrosis, but decrease metastasis, of orthotopically-implanted pancreatic tumors." (PMID 36700235, 2022). "We therefore suggest that the MUC4–miR-210 negative feedback loop is exclusively effective in earlier stages of pancreatic cancer in order to maintain cell homeostasis and inhibit tumor initiation under normoxic conditions." (PMID 34944818, 2021). "In contrast, downregulated miRNA-150 expression has been identified in lymphoma, acute myeloid leukemia, pancreatic cancer, esophageal squamous, colorectal cancer (CRC), and hepatocellular carcinoma, where miRNA-150 targets several oncogenes such as Akt, MUC4, ZEB1, and c-Myb." (PMID 33848981, 2021). "MUC4 regulates CD44 and c-Myc expression via β-catenin in pancreatic cancer cells." (PMID 33082357, 2020). "Besides, the expression of MUC4 is mediated through upregulation of signal transducer and activator of transcription (STAT) in pancreatic cancer and gastric cancer." (PMID 31915505, 2019). "MUC4 is highly regarded as a therapeutic target in pancreatic cancer as it is not expressed in healthy pancreas, while it is neoexpressed in early preneoplastic stages (PanINs)." (PMID 31723153, 2019). "MUC4 is membrane-bound mucin that is overexpressed in pancreatic cancer but absent in normal pancreas and chronic pancreatitis." (PMID 34164227, 2018). "Recent studies have shown MUC4 expression in 91% of tissues of pancreatic cancer patients and increased expression with advancing stages of pancreatic cancer and poor patient survival, but MUC4 is not expressed in normal pancreas." (PMID 34164227, 2018).
pancreatic cancer (continued). "We also found that higher expression of MUC4 was not predictive of pancreatic cancer or cyst status." (PMID 34164227, 2018). "MUC4 expressing pancreatic cancer cells exhibit greater resistance to gemcitabine than MUC4 negative cells, through activation of anti-apoptotic pathways, thereby promoting cell survival." (PMID 29144412, 2017). "IHF analysis was carried out on the frozen pancreatic tumour tissue sections to confirm the expression of MUC4/Y and NOTCH3." (PMID 27287498, 2016). "When the functions of MUC4 (MUC4/Y) and AMOP domain in pancreatic cancer are clarified, we could design some specific sequence such as aptamer/siRNA to silence them, in order to reduce, or even block the malignant biological behavior of pancreatic cancer." (PMID 27287498, 2016). "Previous studies from our lab have shown that MUC4 expression is higher in pancreatic cancer specimens as compared to non-malignant controls." (PMID 25686822, 2015). "Briefly, canertinib and afatinib are irreversible pan-EGFR TKIs that have been shown to be effective in various cancers, but its therapeutic efficacy was not explored in pancreatic cancer in the context of MUC4 mucin." (PMID 25686822, 2015). "Western blot analysis confirmed that the protein level of phospho STAT1, total STAT1 and MUC4 protein is not altered upon erlotinib treatment in CD18/HPAF pancreatic cancer cells for 24h." (PMID 25686822, 2015). "MiaPaCa-1 cells (A MUC4 negative pancreatic cancer cells) were treated with indicated concentration of canertinib and analyzed for pHER2, total HER2, MUC4 and pFAK protein expression." (PMID 25686822, 2015). "As our previous studies have showed MUC4 stabilization and interaction with HER2, we examined whether canertinib could influence the localization pattern of MUC4 and HER2 in pancreatic cancer cells by immunofluorescence analysis." (PMID 25686822, 2015). "Also, earlier evidence indicates that MUC4 stabilizes HER2 thereby mediating cellular signaling for proliferation and metastasis and imparts resistance to gemcitabine in pancreatic cancer cells." (PMID 25686822, 2015). "To determine whether selective silencing of endogenous EGFR led to inhibition of MUC4 mucin expression, we used an EGFR specific siRNA approach in pancreatic cancer cells." (PMID 25686822, 2015). "However, few questions that remained unanswered include i) what is the interplay between MUC4 and HER family proteins, and ii) what are the contributions of other HER family members to the proliferation of pancreatic cancer cells." (PMID 26035354, 2015). "In addition to the transfection studies, treatment of pancreatic cancer cells with canertinib and afatinib at the indicated concentrations also resulted in significant inhibition of phospho-STAT1 and decrease of MUC4 mucin protein expression." (PMID 25686822, 2015). "Based on stable forced-expressed pancreatic cancer PANC-1 cell model, functional studies show that MUC4/Y enhances malignant activity in vitro and in vivo, including proliferation under low-nutritional-pressure, resistance to apoptosis, motility, invasiveness, angiogenesis, and distant metastasis." (PMID 25367394, 2014). "MUC4 has shown to interact with HER2/ErbB2 in ovarian and pancreatic cancers." (PMID 25261375, 2014). "The proportion of cells positive for annexin V and 7-AAD was significantly decreased (P <0.01, respectively) compared to the blank and negative controls, suggesting that MUC4/Y plays an anti-apoptotic role in pancreatic cancer in vitro." (PMID 25367394, 2014).
pancreatic cancer (continued). "As one of its splice variants, MUC4/Y with coding sequence is most similar to that of the full-length MUC4 (FL-MUC4), together with alternative splicing of the MUC4 transcript has been observed in pancreatic carcinomas but not in normal pancreas." (PMID 25367394, 2014). "We have noticed that alternative splicing of the MUC4 transcript has been observed in pancreatic carcinomas but not in normal pancreas." (PMID 25367394, 2014). "Our results show that nicotine-induced MUC4 can promote the proliferation and invasion of pancreatic cancer cells, whereas, RA-induced MUC4 can promote invasion but not proliferation." (PMID 22537161, 2012). "Further, none of the antibodies showed any reactivity with MUC4 negative pancreatic cancer cell lines MiaPaCa or Panc1 (data not shown)." (PMID 21886786, 2011). "Stable ectopic expression of a truncated form of MUC4 (lacking 90% of the tandem repeat (TR) region), resulted in increased growth, motility, and invasiveness of pancreatic cancer cells and in xenografted nude mice." (PMID 24281201, 2010). "On the other hand, MUC4 is minimally or not expressed in the normal pancreas or chronic pancreatitis but is highly expressed in human pancreatic tumours and pancreatic tumour cell lines." (PMID 15494719, 2004). "The MUC4 mucin is expressed at high levels in human pancreatic tumours and tumour cell lines, with an undetectable level in the normal pancreas." (PMID 14760381, 2004). "MUC4 is highly expressed in human pancreatic tumours and pancreatic tumour cell lines, but is minimally or not expressed in normal pancreas or chronic pancreatitis." (PMID 14760381, 2004). "In addition, MUC4 upregulates N-Cadherin expression, which promotes EMT in pancreatic cancer cells." (PMID 40076457, 2025). "First, TQ can downregulate the expression of mucin 4 (MUC4) through the proteasome pathway, which leads to the activation of c-jun NH2 terminal kinases (JNK) and p38 mitogen-activated protein kinase (p38 MAPK) pathways in pancreatic cancer cells, thereby inducing apoptosis." (PMID 36686732, 2022). "Fortunately, mucin 4 (MUC4), a glycoprotein with a high molecular weight, seems to be a novel and attractive tumor-associated antigen, because it is overexpressed in mouse and human pancreatic tumors, not being detected in the normal pancreas." (PMID 34884642, 2021). "In order to establish a link between MUC4 and miR-210-3p in early-stage PDAC, we evaluated miR-210-3p expression level by RT-qPCR and Muc4 immuno-staining scores by immunohistochemistry (IHC) in Pdx1-Cre; K-rasG12D (KC) transgenic mouse model of pancreatic cancer." (PMID 34944818, 2021). "FXR was significantly increased in pancreatic cancer cell lines in comparison to normal pancreatic cells and FXR was found as the regulator of FAK (PTK2, protein tyrosine kinase 2)/c-Jun (JUN, Jun proto-oncogene, AP-1 transcription factor subunit) / MUC4 (mucin 4) signaling pathway." (PMID 31379749, 2019). "Besides, elevated expression of HER3 and MUC4 and their interactions that possibly induced by increased phosphorylation of ERK and expression of PI3K and c-Myc were observed in HER2 knockdown pancreatic cancer cells, leading to increased cell proliferation, motility and tumorigenicity." (PMID 30068375, 2018). "Moreover, MUC4 is expressed in the earliest stage (PanIN1A) of pancreatic cancer but is not specific enough." (PMID 30236127, 2018). "Since our previous study has demonstrated that the MUC4 promoter has STAT1 binding sites and regulates MUC4 expression in pancreatic cancer cells, we investigated whether the levels of phosphorylated STAT1 could influence MUC4 in pancreatic cancer cells treated with the pan-EGFR inhibitors." (PMID 25686822, 2015). "Thus, our data suggest that HER3 interacts with MUC4 and is involved in the proliferation of pancreatic cancer cells in the absence of HER2." (PMID 26035354, 2015).
pancreatic cancer (continued). "In addition, among the 205 upregulated genes, the pancreatic cancer-related gene MUC4 was upregulated by 4.0-fold, indicating that YY1 may negatively regulate MUC4 gene expression." (PMID 24884523, 2014). "Smoking is strongly correlated with pancreatic cancer and in the present study; we elucidate the molecular mechanisms by which nicotine as well as agents like retinoic acid (RA) and interferon-γ (IFN-γ) induce the expression of MUC4 in pancreatic cancer cell lines CD18, CAPAN2, AsPC1 and BxPC3." (PMID 22537161, 2012). "Therefore, to determine the function of MUC4 in the development of resistance to gemcitabine in pancreatic cancer cells, we assessed the effect of MUC4 down-regulation on gemcitabine-induced apoptosis in CD18/HPAF pancreatic cancer cells." (PMID 19738614, 2009). "The membrane-bound mucin, MUC4, which is expressed as early as PanIN-1A but is not expressed in the healthy pancreas, and its membrane partner, the oncogenic receptor ErbB2, which is frequently overexpressed in pancreatic cancer as well as in PanINs, represent promising therapeutic targets." (PMID 24884523, 2014). "We identified and characterized the MUC4-miR-210-3p feedback regulation loop in PDAC cells under normoxia conditions and showed that miR-210-3p inhibits pancreatic cancer cell proliferation and migration." (PMID 34944818, 2021). "We further investigated the miR-210-3p biological roles in vitro in PANC89 (expressing MUC4), PANC-1 and MIA PaCa-2 (not expressing MUC4) pancreatic cancer cells by performing transient and stable transfections." (PMID 34944818, 2021). "Intriguingly, Gal-3 is able to stabilize MUC4 but not MUC1 mRNA, in our pancreatic cancer cell model." (PMID 28262838, 2017). "To identify the importance of HER3 in pancreatic cancer cell proliferation, we transiently knockdown HER3 in HER2 low pancreatic cancer cells, and found that MUC4 protein expression level did not change significantly in these cells." (PMID 26035354, 2015). "Indeed, we identified and characterized a MUC4-miR-210-3p negative feedback loop in PDAC, but we also elucidated the miR-210-3p roles in vitro and in vivo on proliferation and migration of pancreatic cancer cells." (PMID 34944818, 2021). "Additionally, the MUC4 protein expression was not inhibited by erlotinib, a reversible EGFR inhibitor, in pancreatic cancer cells." (PMID 25686822, 2015). "Since, MUC4 acts as an oncogene during the progression and metastasis of pancreatic cancer, we hypothesized that in the absence of HER2, HER3 may interact with MUC4 to promote pancreatic cancer cell proliferation." (PMID 26035354, 2015).